GSK3B (glycogen synthase kinase 3 beta)
Diseases named in the same sentence as GSK3B in open-access papers (continued):
Sharing a sentence is not in itself a finding about the gene and the disease.
renal carcinoma (16 papers, 2009 to 2025). A carcinoma arising from the epithelium of the renal parenchyma or the renal pelvis. "LUCAT1 promotes proliferation and invasion of renal cancer through the AKT/GSK-3β signalling pathway." (PMID 34736453, 2021). "Overexpression of miR-199a suppresses renal cancer cell proliferation and survival by downregulating GSK-3β expression." (PMID 28978024, 2017). "We found GSK-3β aberrant nuclear accumulation in most (91.89%) of human renal carcinomas, whereas GSK-3β was detectable only in cytoplasm in normal kidney tissue." (PMID 19920820, 2009). "We used small molecule inhibitor, RNA interference, western blotting, quantitative RT–PCR, BrDU incorporation and MTS assays to study the effect of GSK-3β inactivation on renal cancer cell proliferation and survival." (PMID 19920820, 2009). "We found that depletion of GSK-3β leads to a significant decrease in renal cancer cell survival accompanied with apoptotic morphological changes as detected by Hoechst staining, whereas depletion of GSK-3α does not affect cancer cells." (PMID 19920820, 2009). "Therefore, the PI3K/AKT and WNT/CTNNB1 pathway work together as a PI3K/AKT/GSK3β/CTNNB1 pathway which induces differentiated renal cancer cells to transform into a more cancer stem-like cells." (PMID 25757764, 2015). "Overall, PIK3R1 down-regulation in RCC promotes propagation, migration, EMT and stem-like phenotype in renal cancer cells through the AKT/GSK3β/CTNNB1 pathway, and may contribute to progression and metastasis of RCC." (PMID 25757764, 2015). "Therefore, in consistence with previous studies, our study suggests that the PI3K-AKT and WNT/CTNNB1 pathways converge on GSK3β in renal cancer cells." (PMID 25757764, 2015). "Moreover, the levels of cytoplasmic GSK-3β in human renal carcinomas were higher than in normal kidney tissues." (PMID 19920820, 2009). "Whether GSK-3β kinase activity is required for its stabilisation in the nucleus of renal cancer cells remains to be investigated." (PMID 19920820, 2009). "Our results suggest that aberrant nuclear accumulation of GSK-3β is a feature of renal cancer cells and GSK-3β activation might be a critical early step of RCC carcinogenesis." (PMID 19920820, 2009). "To determine whether the inhibitory effect on renal cancer cell survival by pharmacological inhibition of GSK-3 was specific to GSK-3β, we depleted GSK-3α or GSK-3β expression in ACHN cancer cells using siRNA." (PMID 19920820, 2009). "Moreover, according to the same study, adiponectin may increase the renal cancer cells’ sensitivity to sunitinib by GSK-3β/β-catenin pathway downregulation." (PMID 40227577, 2025). "However, the subcellular localisation of GSK-3β in renal cancer cells is unknown." (PMID 19920820, 2009). "Our study revealed the intracellular function of APOL1 as a tumor suppressor in renal cancer cell EMT and metastasis through FAK/Akt/GSK3β and NFκB, which may be potentially targeted to control ccRCC metastasis." (PMID 38680858, 2024). "Nevertheless, GSK-3β protein level increased either by the chemical agent such as 6-Gingerol or its upstream molecular lncRNA NBAT1/miR-346 can hinder cell proliferation and migration in renal cancer." (PMID 34555811, 2021). "The downregulation of PIK3R1 promotes EMT, migration, and cancer stem cell phenotype in renal cancer cells and may contribute to the progression and metastasis of RCC by activating the PI3K/AKT/GSK3β/CTNNB1 pathway." (PMID 25757764, 2015). "Our results show nuclear accumulation of GSK-3β as a new marker of human RCC, identify that GSK-3 positively regulates RCC cell survival and proliferation and suggest inhibition of GSK-3 as a new promising approach in the treatment of human renal cancer." (PMID 19920820, 2009). "As GSK-3β is a positive regulator of NF-κB activity, inhibition of GSK-3 may sensitise renal cancer cells to conventional chemotherapeutic agents." (PMID 19920820, 2009).
renal carcinoma (continued). "Our finding of nuclear accumulation of GSK-3β suggests the possibility that GSK-3β could positively regulate NF-κB-mediated transcriptional activation of Bcl-2 and XIAP in the nucleus of renal cancer cells." (PMID 19920820, 2009). "Using nuclear/cytoplasmic fractionation, we found aberrant nuclear expression of GSK-3β in human renal carcinomas but not in their normal counterparts." (PMID 19920820, 2009). "Moreover, we found abberant GSK-3β nuclear overexpression in RCC cell lines and most human renal carcinomas." (PMID 19920820, 2009). "As GSK-3β has a positive role in expression of certain NF-κB-regulated genes, we investigated whether inhibition of GSK-3 affects NF-κB-mediated expression of Bcl-2 and XIAP in renal cancer cells." (PMID 19920820, 2009). "Moreover, we show that depletion of GSK-3β by siRNA leads to a decrease in renal cancer cell survival, suggesting that GSK-3β, but not GSK-3α, is a selective regulator of survival in renal cancer cells." (PMID 19920820, 2009).
chronic kidney disease (15 papers, 2015 to 2025). Impairment of the renal function secondary to chronic kidney damage persisting for three or more months. "For instance, salvianolic acid treatment activates AKT, inhibiting GSK-3β, which leads to Nrf2 nuclear accumulation and expression of protective genes against oxidative stress in chronic kidney disease." (PMID 39769005, 2024). "Thus, GSK3β plays a crucial role in regulating inflammation via the NF-κB pathway, significantly contributing to renal inflammation and chronic kidney disease." (PMID 40526103, 2025). "Its modulation is crucial for normal kidney tissue response to stress; hyperactivation of GSK-3β in conditions like acute kidney injury impairs Nrf2 accumulation, reducing antioxidant gene induction and contributing to oxidative damage and chronic kidney disease." (PMID 39769005, 2024). "In addition, restoration of glucose uptake in neutrophils by pharmacological inhibition of glycogen synthase kinase 3 beta (GSK3β) rescued ROS production and candidacidal function of neutrophils from uremic mice and patients with chronic kidney disease." (PMID 34964702, 2022). "Glycogen synthase kinase 3β (GSK3β) is involved with metabolism and may have a role in kidney senescence, positioning it as a target for complications from chronic kidney disease." (PMID 35166232, 2022). "In mice with chronic kidney disease-induced mitochondrial dysfunction, curcumin could improve mitochondrial biogenesis and mitochondrial function and suppress OS, probably by inhibiting glycogen synthase kinase-3β (GSK-3β) activity." (PMID 39203857, 2024). "Analysis of publicly available kidney transcriptome database demonstrated that patients with progressive chronic kidney disease (CKD) exhibited GSK3β overexpression in renal tubulointerstitium, in which the predefined hallmark gene sets implicated in fibrogenesis were remarkably enriched." (PMID 33931588, 2021). "In fact, treatment with salvianolic acid, through AKT activation and consequent GSK-3β inhibition, induces NRF2 nuclear accumulation and transcription of target genes that protect the kidney epithelium from the oxidative stress produced during chronic kidney disease (CKD)." (PMID 33233657, 2020). "Similarly, clinical studies in patients with chronic kidney disease (CKD) and cognitive dysfunction reported that abnormally elevated levels of Aβ, GSK3-β and tau-p, among others, were reestablished after treatment with rhEPO (100 IU/kg) administered twice weekly for 6 months." (PMID 33255969, 2020). "In tubules featuring acute kidney injury (AKI), induced for example by radiotherapy, hyperactivation of GSK-3β results in impaired NRF2 nuclear accumulation, mitigated induction of antioxidant genes, and consequent oxidative damage, which accounts for the insurgency of chronic kidney disease." (PMID 33233657, 2020). "In addition, one study found that in the renal tubules after acute kidney injury, glycogen synthase kinase 3β (GSK-3β) overactivity impaired NRF2 antioxidant response via a KEAP1-independent mechanism, resulting in persistent oxidative damages that lead to chronic kidney disease (CKD)." (PMID 35721561, 2022).
Glucose intolerance (15 papers, 2011 to 2025). Glucose intolerance (GI) can be defined as dysglycemia that comprises both prediabetes and diabetes. "GSK3β is a potential therapeutic target for common chronic diseases including type 2 DM and Alzheimer's disease, given the causative associations with glucose intolerance, neurodegenerative disorders, and inflammation." (PMID 24212624, 2011). "Depending on its respective primary functions, GSK3β has been implicated in glucose intolerance, neurodegenerative disorders, chronic inflammatory and immunological diseases, and cancer; although the various roles described for GSK3β in cancer remain complex and controversial [reviewed in 8]." (PMID 29568361, 2018). "Interestingly, deletion of GSK-3β from insulin-producing β-cells improved glucose tolerance and increased beta-cell mass in mice fed normal as well as high-fat diet (HFD) while increased hypothalamic GSK-3β led to glucose intolerance and weight gain in leptin-deficient (ob/ob) mice." (PMID 32365965, 2020). "Aberrant expression and activity of GSK3β contributes to the pathogenesis and progression of common diseases such as glucose intolerance and cancer." (PMID 35281088, 2022). "Our findings suggest that although deletion of either GSK-3 isoform protects against HFD-induced glucose intolerance, GSK-3β is clearly the dominant isoform regarding GSK-3 effects on glucose metabolism." (PMID 35159367, 2022). "Aberrant expression and activity of GSK3β contributes to the pathogenesis and progression of common recalcitrant diseases such as glucose intolerance, neurodegenerative disorders and cancer." (PMID 32503133, 2020). "Glucose intolerance (iAUC increased by ∼60%) and blunted insulin-stimulated hepatic Akt and GSK3β phosphorylation (∼40–60%) were found in both feeding conditions (p<0.01 vs Con, assessed after 1 week)." (PMID 22355328, 2012). "In HFD-fed mice, lentinan reduced hepatic inflammation and glucose intolerance by suppressing NF-κB activation and Protein Tyrosine Phosphatase 1B (Ptp1b) expression, thereby restoring insulin signaling via the Akt–glycogen synthase kinase 3 beta (GSK3β) cascade." (PMID 41302443, 2025). "In addition, conditional global deletion of GSK3β protected animals from HFD-induced glucose intolerance, but this effect weakened after chronic HFD consumption." (PMID 37432552, 2023). "In this study, we found that the HF diet promoted steatohepatitis and glucose intolerance in mice, which had M1 proinflammatory macrophage polarization, elevated NFκB and PTP1B level and impaired insulin Akt-GSK3β signaling pathway in the liver." (PMID 35127789, 2021).
Huntington disease (15 papers, 2016 to 2025). Huntington disease (HD) is a rare neurodegenerative disorder of the central nervous system characterized by unwanted choreatic movements, behavioral and psychiatric disturbances and dementia. "GSK3β is abundant in the brain and is associated with AD, PD, and Huntington’s disease (HD), enlarging its pharmacological importance as an NDD target." (PMID 36421986, 2022). "It is worth noting that GSK3β loss has been reported in AD and Huntington’s disease, and this study adds both the PDD and DLB subtypes of LBD to the list." (PMID 27609071, 2016). "In Huntington's disease (HD), there are early hippocampal deficits both in patients and transgenic mouse models, which prompted us to investigate whether disease-specific changes in GSK-3β expression may underlie these abnormalities." (PMID 27124580, 2016). "In contrast to the current findings in LBD, reductions of GSK3β correlated with decreased pCRMP2 in Huntington’s disease." (PMID 27609071, 2016).
acute kidney injury (14 papers, 2013 to 2025). Sudden and sustained deterioration of the kidney function characterized by decreased glomerular filtration rate, increased serum creatinine or oliguria. "GSK3β activity has been reported to be activated in response to ROS to inhibit NRF2 by preventing its translocation to the nucleus in a model for acute kidney injury as well as in cortical neurons." (PMID 37163077, 2024). "Our previous study demonstrated that GSK-3β inhibition enhanced autophagy and improved cell survival in acute kidney injury." (PMID 38125704, 2023). "Glycogen synthase kinase-3β (GSK3β) is a serine/threonine protein kinase that plays an important role in renal tubular injury and regeneration in acute kidney injury." (PMID 26092126, 2015). "Some studies have suggested that the ubiquitination and subsequent degradation of GSK3β may activate Wnt/β-catenin signaling, which in turn contributes to the progression of acute kidney injury (AKI)." (PMID 40526103, 2025). "On the one hand, it has been shown that the inhibition of such a proapoptotic and antiproliferative signaling factor as GSK-3β could be protective in acute kidney injury." (PMID 25505675, 2013). "In our previous study, we reported that S100A16 promotes acute kidney injury (AKI) by activating E3 ubiquitin ligase, the HMG-CoA reductase degradation protein 1 (HRD1), induced ubiquitination and degradation of GSK3β and CK1α, two β-catenin complex members." (PMID 38710691, 2024).
amyloid (14 papers, 2017 to 2025). "collectively, these results points towards an alteration in GSK-3β ability to shift the synaptic plasticity threshold as a potential cause underlying the pathogenesis of early amyloidosis." (PMID 40414897, 2025). "Furthermore, GSK-3β arises as a promising biomarker of aberrant plasticity and memory caused by early amyloidosis." (PMID 40414897, 2025). "Insulin gene knockout mice were found to show an increase in GSK-3β activity and tau hyperphosphorylation, with excessive deposition of amyloid plaques in hippocampal neurons." (PMID 38536493, 2024). "It regulates the PI3K/Akt/GSK-3β and NF-κB pathways, inhibits neuroinflammation, amyloidosis, synaptic dysfunction, and improves cognitive impairment." (PMID 38005352, 2023). "The data of real-time PCR suggested that the amyloid-related neurogenesis reduction was the result of upregulated GSK-3β in concurred with the previous study." (PMID 35883119, 2022). "GSK-3β is the earliest discovered Tau protein-related kinase, which participates in Tau protein-related pathological changes and amyloid pathological changes." (PMID 34839794, 2021). "Accordingly, hippocampal GSK-3β was found to be overactivated in AD-like amyloidosis mice." (PMID 40414897, 2025). "It is well known that GSK-3β is a proline-directed serine/threonine kinase with structural activity, which enhances tau phosphorylation and regulates the amyloidosis of APP by regulating the expression of BACE and the function of gamma-secretase in vivo and in vitro." (PMID 34987593, 2021). "The molecular mechanism whereby amyloid and Tau pathologies contribute to AD might depend on the influence of Aβ on kinases such as GSK-3β, which might result in the phosphorylation of tau at many sites, including T181 and pT217." (PMID 32183883, 2020). "The increase in PGRN expression induced by ND-602 in this study could have reduced amyloid plaque burden through phosphorylation of GSK3β, thereby reducing its activity." (PMID 28837568, 2017). "Based on the in vivo experiment in the ICV-STZ rat model of AD, modulation of the PI3K/Akt/GSK3β signaling pathway could diminish oxidative stress, neuro-inflammation, and apoptosis, Moreover, amyloid plaque number and phosphorylated tau expression were marked decrement." (PMID 36570530, 2022). "Phosphorylation of tau protein by GSK-3β and the protective effect of insulin are well established, while involvement of GSK-3α in amyloid plaque formation is also suggested; thus, its inhibition is clearly connected to the anti-AD effect." (PMID 41226821, 2025). "Blockade of the GSK3β pathway in APP transgenic mice resulted in a reduction in Aβ production and amyloid plaque load." (PMID 37432552, 2023).
cardiomyopathy (14 papers, 2017 to 2025). A disease of the heart muscle or myocardium proper. "In cardiomyopathy, glycogen synthase kinase 3 beta (GSK3β)-induced HK2 dephosphorylation can cause mitochondrial HK2 liberation, indicating that an altered HK2 activity is a key factor for mitochondrial HK2 expression and translocation." (PMID 34741026, 2021). "NDRG2 can also activate glycogen synthase kinase 3β (GSK-3β), impacting β-catenin signaling and potentially contributing to cardiomyopathy establishment as the GSK3 family has been implicated in the regulation of cardiac remodeling downstream of the PI3K–Akt pathway." (PMID 32433643, 2020). "Replenishment of vaspin attenuated lipoatrophy-induced cardiomyopathy by modulating cardiac AKT/GSK3β activity." (PMID 34631690, 2021). "In summary, our research shows that GSK‐3β is excessively activated in endotoxin‐induced cardiomyopathy." (PMID 31503410, 2019). "Sulforaphane prevents angiotensin II-induced cardiomyopathy partially through the Akt/GSK-3β/Fyn pathway-mediated upregulation and activation of Nrf2." (PMID 30622677, 2018). "In addition, SFP can partially prevent cardiomyopathy through the signaling of Akt/GSK-3β/Fyn and activation of Nrf2." (PMID 35441581, 2022). "By activating the PI3K/Akt/GSK-3β/NRF2 intracellular signaling pathway, NRF2 activation and up-regulation of NRF2 expression can prevent cardiomyopathy and can also increase the expression of HO-1 to play a neuroprotective role." (PMID 39670103, 2024). "Both in in vivo and in vitro model of DOX-induced cardiomyopathy and cardiomyocyte apoptosis, we demonstrated that SMI could alleviate DOX-induced cardiotoxicity, improve cardiac function, and maintain mitochondrial homeostasis through activation of AMPK and PI3K/Akt/GSK-3β signaling pathway." (PMID 32581790, 2020).
Hypoglycemia (14 papers, 2016 to 2025). A decreased concentration of glucose in the blood. "Conversely, mice experiencing hypoglycemia due to combined inhibitor treatment exhibited reduced liver glycogen storage and lower levels of p-GSK3β, further suggesting that liver glycogenolysis contributed to the recovery of normal blood sugar." (PMID 38755637, 2024). "Under hypoglycemia/metformin treatment, upregulated Ppp2r5d dephosphorylates GSK-3β, leading to a decline in MCL-1 and cell death." (PMID 39200351, 2024). "Of note, concerns had been raised regarding the potential toxicity of GSK-3β inhibitors ranging from hypoglycemia to tumorigenesis and neuron deregulation." (PMID 38367137, 2024). "Our findings suggest that DSS potentially confers cognitive protection by alleviating central hypoglycemia through the IRS1/GSK3β/Wnt3a‐β‐catenin pathway." (PMID 39344343, 2024). "A study found that a hypoglycemia-metformin combination restrains tumor growth by activating glycogen synthase kinase 3β (GSK3β) downstream of PP2A." (PMID 38192642, 2023). "Developing GSK-3β inhibitors is challenging due to some potential reports of toxicity such as hypoglycemia, tumorigenesis, and neuron deregulation." (PMID 30413117, 2018). "A previous study demonstrated that metformin combined with hypoglycemia impaired tumor metabolic plasticity and growth by modulating the Protein phosphatase 2A (PP2A)-glycogen synthase kinase 3beta (GSK3β)-myeloid cell leukemia 1 (MCL-1) axis." (PMID 39308524, 2024). "Mechanistically, metformin activates the PP2A-GSK3β-MCL-1 pathway by inhibiting cancerous Inhibitor Of PP2A (CIP2A), a PP2A inhibitor, and hypoglycemia upregulates the B56δ, a PP2A regulatory subunit, eventually, the active PP2A-B56δ has higher affinity for GSK3β." (PMID 36484892, 2022). "Meanwhile, morusin, kuwanon C and morusyunnansin L are probably the important ingredients of MLF in hypoglycemia, which may function by regulating key targets, including ADORA1, AKT serine/threonine kinase 1 (AKT1), PPARγ and glycogen synthase kinase-3 beta (GSK3β)." (PMID 36278175, 2022).